SMDT1 (single-pass membrane protein with aspartate rich tail 1)
Description:
Essential regulatory subunit of the mitochondrial calcium uniporter complex (uniplex), a complex that mediates calcium uptake into mitochondria. Required to bridge the calcium-sensing proteins MICU1 with the calcium-conducting subunit MCU. Acts by mediating activation of MCU and retention of MICU1 to the MCU pore, in order to ensure tight regulation of the uniplex complex and appropriate responses to intracellular calcium signaling.
Synonyms: C22orf32; EMRE; dJ186O1.1; DDDD
Tractability: Small molecule: a structure with a bound ligand is known. Antibody: UniProt predicts a signal peptide or a membrane-spanning region. PROTAC: its protein half-life has been measured.
Gene: Protein-coding gene on chromosome 22 (42,079,564 to 42,088,243, forward strand). Ensembl gene ENSG00000183172.
Subcellular location: Mitochondrion inner membrane
Subcellular location (Human Protein Atlas): Mitochondria; Nucleoplasm
Pathways (Reactome):
Transport of small molecules: Mitochondrial calcium ion transport; Processing of SMDT1
Metabolism of proteins: Mitochondrial protein degradation
Gene Ontology:
Molecular function: channel activator activity; protein binding; protein-macromolecule adaptor activity
Biological process: calcium import into the mitochondrion; cellular response to calcium ion starvation; mitochondrial calcium ion homeostasis; mitochondrial calcium ion transmembrane transport
Cellular component: mitochondrial inner membrane; mitochondrion; uniplex complex; mitochondrial matrix
Genetic constraint (gnomAD): Loss-of-function variants: 6 observed, 6.21 expected, observed/expected ratio (o/e) 0.97, 90% interval 0.52 to 1.75. That is too few expected variants to judge how well the gene tolerates losing a copy. Missense variants: 159 observed, 154.36 expected, observed/expected ratio (o/e) 1.03, 90% interval 0.9 to 1.17. Synonymous variants: 81 observed, 67.86 expected, observed/expected ratio (o/e) 1.19, 90% interval 1 to 1.44.
Homologues: Orthologues: chimpanzee SMDT1 (98% identical), macaque SMDT1 (94% identical), dog SMDT1 (92% identical), pig SMDT1 (88% identical), guinea pig SMDT1 (86% identical), mouse Smdt1 (81% identical), tropical clawed frog smdt1 (58% identical), zebrafish smdt1a (47% identical), zebrafish smdt1b (46% identical), Drosophila melanogaster EMRE (39% identical), Caenorhabditis elegans emre-1 (26% identical).
Diseases named in the same sentence as SMDT1 in open-access papers:
SMDT1 is named in the same sentence as 20 diseases in open-access papers, as found by Europe PMC text mining. Sharing a sentence is not in itself a finding about the gene and the disease. The quoted sentences say what the papers report.
cardiomyopathy (1 paper, 2025). A disease of the heart muscle or myocardium proper. "Additionally, Mendelian randomization (MR) analysis revealed a causal relationship between elevated levels of the SMDT1-encoded MCU regulator and increased risks of cardiovascular diseases, including coronary atherosclerosis, myocardial infarction, and cardiomyopathy." (PMID 40422231, 2025).
Sepsis (1 paper, 2021). Sepsis is defined as life-threatening organ dysfunction caused by a dysregulated host response to infection. "The sub analysis of healthy versus CCI CD4+ T-lymphocytes revealed unique differential expression of five genes not seen in the analysis of all late sepsis patients (upregulated: HBB, ETS1; downregulated: SMDT1, RPL41, MTRNR2L12)." (PMID 34484194, 2021).
cardiovascular disease (1 paper, 2025). "This represents a significant methodological advancement, establishing for the first time a causal relationship between genetically predicted SMDT1-encoded MCU regulator levels and various cardiovascular diseases." (PMID 40422231, 2025). "MR analysis demonstrated a causal relationship between elevated SMDT1-encoded MCU regulator levels and increased cardiovascular disease risk." (PMID 40422231, 2025). "In this context, our MR findings, suggesting a causal relationship between SMDT1-encoded MCU levels and cardiovascular diseases, align with previous literature on MCU function, while significantly extending this understanding into the realm of genetic predisposition to SCD-CAD." (PMID 40422231, 2025).
SMDT1 also shares sentences with these, for which no sentence is quoted: tumor (4 papers); infection (3); breast carcinoma (2); cancer (2); atherosclerosis (1); cervical cancer (1); coronary atherosclerosis (1); gastric cancer (1); hereditary spastic paraplegia (1); influenza infection (1); limb-girdle muscular dystrophy (1); melanoma (1); muscular dystrophy (1); myocardial infarction (1); neurodegenerative disease (1); spinocerebellar ataxia (1); steatosis (1).